IL33 (interleukin 33)
Diseases named in the same sentence as IL33 in open-access papers (continued):
Sharing a sentence is not in itself a finding about the gene and the disease.
infection (continued). "In this study, significant increase in the levels of pro-inflammatory type 1 (TNF-α, IFN-γ, IL-6, IL-1β), pro-inflammatory type 2 (IL-33) and anti-inflammatory type 2 cytokines was observed in unimmunized mice after bacterial challenge indicating the spread of infection." (PMID 26904021, 2016). "Since Orientia lacks the classical ligands for TLR2/4 stimulation, we speculated that the host DAMP molecule, IL-33 plays a role in modulating inflammation responses in this infection." (PMID 26943125, 2016). "Although we indentify macrophages expressing higher levels of IL-33 after infection, we cannot exclude that other CNS resident cells such as glial cells and astrocytes could be the main source of IL-33 production." (PMID 27334012, 2016). "To determine whether IL-33 was required for activating ILC2s during RSV infection, we measured the total number of IL-13+ ILC2s in the lungs at day 4 after infection in WT and IL-33 KO mice." (PMID 27156176, 2016). "Thus the IL-33 pathway appears to be an ideal target for parasite immunomodulation to allow persistence of infection." (PMID 27476889, 2016). "It was reported that signaling through Toll-like receptors (TLRs) 2 and 4 could modulate IL-33 expression in response to infection in human monocytes." (PMID 26793709, 2015). "Under normal conditions, IL-33 is stored in the nucleus acting as a transcription factor, while upon cellular stress or damage (such as infection and injury), it can be released in the extracellular space through cellular necrosis or unconventional secretory mechanisms and function as alarmin." (PMID 26610488, 2015). "IL-33 has been observed to supply protection during gastric infection and may be an important mediator of the immune functions after damage or infection in epithelial cells." (PMID 27014647, 2015). "We hypothesized that IL-33 could divert the deleterious Th1-immune response during infection and therefore protects mice from ECM." (PMID 25659095, 2015). "Similar results were obtained when the IL-33 treatment began one day after infection (day +1)." (PMID 25659095, 2015). "DEREG mice were infected with PbA and treated daily with PBS or IL-33 from the start of infection." (PMID 25659095, 2015). "Moreover, using different protein kinase inhibitors that target elements downstream of TLR signaling, we show that the TAK1→IKKβ→TPL2→MKK1/MKK2 pathway regulates IL-33 expression following an infection with P. aeruginosa." (PMID 26793709, 2015). "Depending on the disease model, IL-33 either protects against infection or exacerbates inflammatory disease, but it is unknown how the IL-33/ST2 axis regulates the immune response during HTNV infection." (PMID 25658420, 2015). "In accordance with the elevated numbers of neutrophils and eosinophils in the peripheral blood and histological sections, we detected prominent increases in TH2 cytokines, such as IL-4, IL-5, IL-13 and IL-33, during the acute phase of infection, particularly from the 3rd day p.i. onward." (PMID 26135397, 2015). "In the children infection groups, the amounts of IL-27 and IL-33 as produced by their PBMC increased in order G0 < G1 < G3+; the IL-27 production remained unchanged post anti-parasite treatment (pT), whilst the cellular IL-33 production returned pT to the lowest levels as found in G0 children." (PMID 25698903, 2015). "After 1 day of infection, IL33 mRNA expression was increased relative to uninfected controls." (PMID 28210674, 2015). "Levels of IL-33 during infection was influenced by age at the time of initial infection; and this, in turn, correlated with an increase in the numbers of lung ILC2s coinciding with enhanced IL-13 expression and increased lung dysfunction (i.e. AHR) and pathology." (PMID 26473724, 2015). "Interestingly, IL-33 administration to adult mice during primary infection resulted in exacerbated AHR, significantly above that of the NRR group." (PMID 26473724, 2015).
infection (continued). "We speculate that full-length, unprocessed IL-33 is passively released by necrotic cells into the extracellular milieu as an alarmin molecule to indicate cellular stressors (i.e. infection or injury)." (PMID 24586149, 2014). "Next, we investigated whether there were changes in the cytokine milieu at the site of infection using the thoracic cavity lavage and assessed the levels of several cytokines: IL-4, IL-5, IL-13, IL-25, IL-33, and IFNγ." (PMID 24663956, 2014). "Intracellular stores of IL-33 are released from epithelial cells upon infection or injury." (PMID 23653627, 2013). "Interestingly, the mRNA expression of IL-33 was significantly up-regulated following L2-MHV3 infection reaching maximum at 72h post infection (p <0.001)." (PMID 24058536, 2013). "In sum, it seems that IL-33 is passively released from the epithelial barrier which undergo tissue injury, necrosis, and infection and participates in inflammatory processes after taking a more mature form in the extracellular environment with help from neutrophils." (PMID 23653627, 2013). "Monitoring the sequential changes in the expression of cytokines following the infection showed that IL-33 expression peaked at day 6 PI, followed by the peak IL-4/IL-13 expression, suggesting that IL-33 plays a role in the initiation/amplification of the type 2-mediated immune response." (PMID 23536877, 2013). "Consistent with this, iSCs internalize and respond rapidly to in vitro infection with the flagellated bacterium Salmonella typhimurium, increasing their expression of IL-1β and IL-33 at both the mRNA and protein level, with this sensing dependent on RIPK2/p38MAPK signaling." (PMID 24137162, 2013). "IL-33 enhances mucosal defenses against intestinal parasites and bacteria, as described for Toxoplasma gondii, Pseudomonas aeruginosa, and Leptospira infection, indicating a primary role in mucosal protection." (PMID 23847622, 2013). "IL-33 has been shown to enhance mucosal defenses against intestinal parasites and bacteria, as described for Toxoplasma gondii, Pseudomonas aeruginosa and Leptospira infection, indicating a primary role of protection." (PMID 23062310, 2012). "In addition to these findings, increased production of IL-33 early during infection in resistant strains of mice has been correlated with increased production of the Th2-inducing cytokine TSLP." (PMID 23053395, 2012). "IL-33 has also been described as a prototypic ‘alarmin’ that has the ability to signal local, innate immune responses of trauma or infection in an effort to mount an effective, physiologic inflammatory reaction to induce mucosal healing and restore normal gut equilibrium." (PMID 23062310, 2012). "Based on this tissue distribution, we speculate that IL-33 may function as an endogenous ‘alarmin’, similarly to chromatin-associated cytokine HMGB1, to alert the immune system of tissue injury or infection." (PMID 18836528, 2008). "This additionally suggests that IL33 might influence apoptosis signaling during infection." (PMID 41204030, 2025). "However, IL‐33 KO mice in this study do not appear to be susceptible to HD Tm, suggesting IL‐33 does not drive immunity during unmodulated HD Tm infection." (PMID 40944312, 2025). "We then tested if IL-33 could be used after a primary infection to prevent reinfection." (PMID 40048372, 2025). "Infection with HTLV-1A/CoI-L resulted in low overall frequency of monocytes, DCs, and neutrophils producing IL-10, with elevated frequencies of those producing TNF-α in both compartments, linked to high expression of IL-6, CCL2, and IL-33 in blood and of MMP1, IL-1β, CCL3, and CCL19 in the lung." (PMID 41006234, 2025). "We hypothesized that ILC2s respond to IL-33 to promote anti-toxin B antibodies and protect from reinfection, in part due to their known role in adaptive immunity and due to the observed increase in ILC2s in the IL-33–treated group after infection in the MLN and colon." (PMID 40048372, 2025).
infection (continued). "The primacy of the IL‐25 response circuit to Nb immunity has largely rendered questions around IL‐33 responses to the parasite secondary, but interesting research has emerged drawing into focus some points of contention in IL‐33 research, using the Nb infection model." (PMID 40944312, 2025). "The expression profile suggests that IL-33 acts mainly as an alarmin, released when stimulated by infection or tissue damage, and may be involved in the production of sST2, an antagonist of IL-33/ST2 signaling, from Thy-1.2– fibroblast/stromal cells in the PRT." (PMID 38548743, 2024). "Moreover, induction of IL-33 during infection is under the exclusive control of EPAC." (PMID 38750790, 2024). "Since the epithelial cell-derived cytokine IL-25 and IL-33 were known to mediate the progression of cryptococcal diseases caused by C. neoformans infection by amplifying Th2-type immune response, we further analyzed how IL-25 acted together with IL-33 to regulate CD4+ T helper cell during infection." (PMID 37337050, 2023). "Conversely, the expansion of ILC2s via treatment with the cytokine IL-33, or by adoptive transfer of ILC2s, resulted in significantly enhanced bacterial burdens in the lung, liver, and spleen, suggesting that ILC2s may favor severe infection." (PMID 36602520, 2023). "IL-33, as a stomach alarmin, is increased with high fold immediately after gastric insult and infection to effectively activate ILC2s and T cells to initiate type 2 immune response, which may be beneficial by preventing unchecked Th1/Th17 inflammation and showing protective effects." (PMID 37047625, 2023). "Therefore, we studied a 4-month course of infection in wild-type (WT) and IL-33−/− mice." (PMID 36786637, 2023). "These IL-33-deficient mice failed to undergo LCM expansion during infection." (PMID 36948193, 2023). "Recently, however, two studies have reported RV-C15 – a prevalent strain in humans that may cause severe symptoms – infection of C57BL/6J mice induced the upregulation of remodeling-associated genes MUC5AC and MUC5B, elevated IL-25, IL-33, and TSLP levels, and increased numbers of lung ILC2s." (PMID 37773065, 2023). "IL-33 is an alarmin cytokine produced by several different cell types, including epithelia, endothelia, fibroblasts and hematopoietic cells such as mast cells, neutrophils, monocytes, macrophages and dendritic cells, following cell damage resulting from infections or inflammation." (PMID 36359220, 2022). "Furthermore, IL-33 amplifies MC activities during infection and allergy." (PMID 35886897, 2022). "Future research should be devoted to deciphering the roles of IL-33 in neuroinflammatory pathways and in vascular permeability increase which leads to fatal œdema and in host-defense mechanisms such as autophagy or the production of auto-antibodies in the course of infection." (PMID 36362246, 2022). "Hence, the presence of the ST2- IL-9+ ILC2 population in the small intestine described here might be explained by this regulatory loop, where IL-33 and IL-25 are induced upon infection, promoting iILC2s that lack ST2 and express effector cytokines in vivo." (PMID 35711429, 2022). "It is also possible that increased systemic expression of IL-33 and IL1RL2 could be attributed to the patient’s adaptive immune responses to minimize infection associated with the infiltration of bacteria into the periprosthetic tissue from the percutaneous stoma." (PMID 35617338, 2022). "Several studies demonstrated that IL-33 is passively released after tissues damage, which may suggest that this alarmin cytokine alerts the immune system after endothelial or epithelial cell damage during infection, physical stress, or trauma." (PMID 34956079, 2021).
infection (continued). "Due to the importance of IL-33 as a player in a wide variety of immunological processes (inflammation and defense against infection, immune regulation via regulatory T cells), the effects of inhibiting IL-33 may also be diverse and should be carefully considered with regard to safety issues." (PMID 33615121, 2021). "Thus, we next analyzed whether an active inhibition of endogenous IL-33 signaling during CR infection using a ST2 blocking antibody (ST2-Ab) confers protection to the intestinal epithelium." (PMID 33654214, 2021). "However, during Schisotosoma infection, IL-33 seems to contribute to the development of pathology via the induction of type 2 innate lymphoid cells and alternative activation of macrophages, thus favoring the infection." (PMID 34943041, 2021). "Additionally, IL-33-treated mice presented a reduction in parasitemia at the initial step of infection, but they presented hyperparasitemia and died at the late stages of infection." (PMID 32599864, 2020). "The role of IL-33/ST2 axis in early onset infection remains unclear." (PMID 32363166, 2020). "Therefore it may be that H. polygyrus acts on immune cells outside of the intestine, rendering them unresponsive to IL-33, and suppressing their activity prior to their recruitment to the site of infection." (PMID 32420871, 2020). "Since the microbiota plays a critical role in the pathogenesis of CDI24,25, we assessed whether IL-33 treatment altered the microbiota prior to infection via analysis of the V4 region 16S rRNA gene amplified from cecal contents of IL-33 vs. vehicle-treated mice." (PMID 31221971, 2019). "Furthermore, we suggest IL-33 may be a crucial mediator of the immune response in infection, after gastric mucosal damage." (PMID 31320834, 2019). "Thus, IL-33 may be a crucial mediator of the immune response in infection, after damage to the mucosal epithelial tissues." (PMID 31320834, 2019). "Furthermore, we suggest that IL-33 may be a crucial mediator of the immune response against an infection, after gastric mucosal damage." (PMID 31320834, 2019). "Therefore, we speculate that the source of IL-33 that activates hepatic ILC2s at day 32 after infection derives from the necrosis or active necroptosis of HSCs." (PMID 29554131, 2018). "Thus, IL-33 plays its alarmin role only during the early phase of the infection." (PMID 28553430, 2017). "It was also shown using the N. brasiliensis infection model that loss of both IL-33 and IL-25 signaling on ILC2s completely abrogated the early response against this infection due to impaired expansion of ILC2s and lack of IL-13 production, and adoptive transfer of WT ILC2s rescued this phenotype." (PMID 28484466, 2017). "Thus, it is tempting to speculate that also during T. muris infections, AREG may contribute to host resistance by licensing activated Th2 cells to express IL-13 at the site of infection in an IL-33-dependent way." (PMID 29045902, 2017). "However, depending on the organ involved and the Th1/Th2 immune balance necessary to control the infection, IL-33 may also present opposing roles." (PMID 27334012, 2016). "The high levels of constitutive IL-33 may act as a novel alarmin (intracellular alarm signal released after cell injury) to alert the immune system after endothelial or epithelial cell damage during trauma or infection." (PMID 26425339, 2015). "Therefore, upon injury or infection, IL-33 is released from the nucleus of endothelial cells to the extracellular space where it can signal and activate immune cells, such as mast cells, eosinophils, basophils, natural killer cells, and T cells (as many other functions described in this review)." (PMID 26082774, 2015). "Thus IL-33 is critical for worm expulsion, while also minimizing host damage early in infection." (PMID 25028340, 2014).
infection (continued). "Interestingly, the efficacy of IL-33 in this infection model (and others) seems to be highly time-dependent, with administration of exogenous IL-33 at late time points post-infection being ineffective in promoting type 2 responses that would otherwise resolve infection." (PMID 25101088, 2014). "Overall, st2−/− mice tended to have higher mediator levels in lungs than WT mice; especially 14 days after infection with influenza A modest but statistically significant differences were seen in pulmonary IL-6 (P<0.001), IL-1β (P<0.01), KC (P<0.05), IL-10 (P<0.05) and IL-33 (P<0.05) concentrations." (PMID 23483993, 2013). "Thus iSCs elaborate IL-1β and IL-33 protein in response to infection with live Salmonella." (PMID 24137162, 2013). "Interestingly, IL-33-expressing hepatocytes decreased at the same time than NK cells decreased in liver following L2-MHV3 infection, supporting the hypothesis of a regulatory role of NK cells in IL-33 expression in hepatocytes." (PMID 24058536, 2013). "We found that expression of IL-33 was rapidly induced at both the mRNA and protein level upon infection of iSCs with Salmonella, and IL-33 may itself be a candidate for a mucosal healing or repair factor, given its role as a major mediator of epithelial regeneration and homeostasis in the gut." (PMID 24137162, 2013). "Notably, mice deficient in IL-25 (IL-17BR−/−) or IL-33 (T1/ST2) receptors mount poor type 2 responses and are more susceptible to infection with Nippostrongylus brasiliensis, while immunity can be restored to these animals by transfer of ILCs acting in an IL-13-dependent manner [13••]." (PMID 22795966, 2012). "The constitutive expression of IL-33 in epithelial barriers of our body thus supports the possibility that, similarly to the IL-1s, it may play important roles in the response to injury or infection." (PMID 18836528, 2008). "An alternative and more likely possibility is that IL-33 may be released from dead or dying cells during trauma or infection, and may function, similarly to HMGB1, as an endogenous ‘danger’ signal or ‘alarmin’, to alert the immune system of cell or tissue damage." (PMID 18836528, 2008). "Following infections of RSV, ILC2s are activated by epithelial-derived alarmins including IL-33 and TSLP, while a subset differentiates into mILC2s with long-term persistence." (PMID 40636260, 2025). "Four weeks post infection with M.tb HN878, we observed a significant increase in circulating IFN-γ, TNF-α, IL-1β, IL-2, IL-6, IL-12p70, IL-17A/F, IL-15, and IL-33 levels in mice immunized with ID93+EmT4TM compared to saline controls." (PMID 40285479, 2025). "Inflammation is an important defense against infection, and the ST2/IL-33 pathway plays a pivotal role in the response to microbial infections following the release of IL-33 upon exposure to viruses, bacteria, fungi, or parasites." (PMID 41163220, 2025). "For example, mortality due to Streptococcus pyogenes infection was increased in ST2 and IL-33 knock-out mice compared with wild-type and ST2 was shown to be required for efficient infection control during mouse cytomegalovirus infection." (PMID 41163220, 2025). "Early recombinant IL-33 treatment increased trTregs, type 2 innate lymphoid cells, and parasite-specific CD8+ cells at specific time points after infection, leading to reduced tissue damage, lower parasite burden, and improved disease outcome." (PMID 39883714, 2025). "Despite these findings, the specific role of trTregs and the IL-33/ST2 axis in tissue repair and homeostasis during infections remains poorly understood." (PMID 39883714, 2025). "In mice, infection with N. brasiliensis results in ILC2 and eosinophil recruitment to the FRT and increased IL-4, IL-5, and IL-33 in the tissue and/or lavage." (PMID 38277692, 2024). "Infection-induced cAMP was involved in IL-33 production and of its downstream effectors PKA and EPAC, only the latter was responsible for elevated IL-33 level." (PMID 38750790, 2024).